PPARG (peroxisome proliferator activated receptor gamma)
Diseases named in the same sentence as PPARG in open-access papers (continued):
Sharing a sentence is not in itself a finding about the gene and the disease.
cervical carcinoma (23 papers, 2012 to 2025). A carcinoma arising from either the exocervical squamous epithelium or the endocervical glandular epithelium. "In cervical cancer, overexpression of PPARG is implicated in tumourigenesis, cell growth and survival, proliferation and drug resistance in cervical cancer cell lines (HeLa, SiHa, and Me180)." (PMID 40446016, 2025). "In the field of cancer research, it has been found that high expression of miR-27b can inhibit the expression of PPARγ, promote the proliferation and invasion of cervical cancer cells, and increase the risk of cervical cancer." (PMID 40806224, 2025). "Not only is it downregulated in cervical cancer cells, but treatment with a PPARγ agonist seems to enhance apoptosis while PPARγ inhibition supports tumour progression." (PMID 38474047, 2024). "Another study also showed that PPARG, as a target of miR-27b-3p, played a significant role in suppressing cervical cancer progression." (PMID 32850439, 2020). "High-risk HPV infection is reported to upregulate miR-27b levels in HPV-positive cervical cancer tissues which, in turn, increases cell proliferation and decreases apoptosis by inhibiting PPARγ expression." (PMID 31766385, 2019). "Taken together, these results indicate that ciglitazone induces apoptotic cell death through PPARγ-independent mechanisms in cervical cancer cells." (PMID 29296202, 2017). "The few published data reporting the effect of ciglitazone in cervical cancer cells (C-33 A, C-4II, HeLa) showed either an inhibition of the proliferation or an apoptotic death in a PPARγ-independent manner." (PMID 29296202, 2017). "In this study, we investigated the pro-apoptotic activity of TZD in several cervical cancer cell lines (HeLa, Ca Ski, C-33 A) and demonstrated that only ciglitazone individual treatment induced Ca Ski cell apoptosis through PPARγ-independent mechanisms." (PMID 29296202, 2017). "In comparison with normal tissues, cervical cancer tissues have lower PPARγ levels." (PMID 39185567, 2025). "Inhibition of PPARG has been shown to trigger apoptosis, induce G2/M arrest and mitotic catastrophe, and reduce the migratory and invasive potential of pancreatic, colorectal, oesophageal, hepatocellular, and cervical carcinomas." (PMID 40446016, 2025). "In cervical cancer, some evidence has found PPARγ to be anti-proliferative." (PMID 38474047, 2024). "PPARγ, as a target of hsa‐miR‐27b, can downregulate the sodium‐hydrogen exchanger isoform 1 (NHE1) which leads to suppression of cervical cancer." (PMID 39185567, 2025). "In HPV16‐positive cervical cancer tissues, overexpression of hsa‐miR‐27b increases NHE1 expression and lowers the expression of PPARγ which increases invasion and proliferation of cervical carcinoma cells." (PMID 39185567, 2025). "Of note, PPARG exon 6 and TRAF3IP2 exon 2 specifically overlap AP-1 ChIP-seq peaks in human cervical cancer cells (HeLa) cells." (PMID 25340400, 2014). "By using cervical cancer cells and differentiated macrophages, we demonstrate that MMC induces the expression of FasL via upregulation of PPARγ in both cell types (effector cells) in vitro, but it failed to induce bystander killing in cervical cancer cells." (PMID 26492368, 2015).
amyotrophic lateral sclerosis (22 papers, 2008 to 2024). Amyotrophic lateral sclerosis (ALS) is a neurodegenerative disease characterized by progressive muscular paralysis reflecting degeneration of motor neurons in the primary motor cortex, corticospinal tracts, brainstem and spinal cord. "A study using a Drosophila model of amyotrophic lateral sclerosis showed that PPARγ activation exerts neuroprotective effects." (PMID 39561115, 2024). "Moreover, in a mice model of amyotrophic lateral sclerosis (ALS), a disease that causes paralysis due to loss of motor neurons, treatment with PPARγ agonists like rosiglitazone extends survival and decreases motor neuron loss." (PMID 25246934, 2014). "Concomitantly, studies of PPARγ activation showed effects against oxidative stress, mitochondrial dysfunction, and apoptosis in several cell models that resemble AD, Huntington’s disease (HD), amyotrophic lateral sclerosis (ALS), and spinal cord injuries (SCI)." (PMID 28357806, 2018). "The authors of this study proved that the progression of amyotrophic lateral sclerosis (ALS) leads to the activation of PPARγ in motor neurons, which contributes to the increase in the activity of lipid detoxifying enzymes, such as lipoprotein lipase and glutathione S-transferase α-2." (PMID 39062500, 2024). "In a Drosophila model of amyotrophic lateral sclerosis (ALS) based on TDP-43 (TAR DNA-binding protein 43), activation of PPARγ was found to generate neuroprotective benefits." (PMID 34944727, 2021). "Moreover, the synthetic PPARγ agonist pioglitazone was shown to extend the survival of SOD1-G93A, a mouse model of Amyotrophic lateral sclerosis (ALS), by delaying the onset of the disease and preventing the death of motor neuron cells." (PMID 33799988, 2021).
congestive heart failure (22 papers, 2008 to 2024). Failure of the heart to pump a sufficient amount of blood to meet the needs of the body tissues, resulting in tissue congestion and edema. "TZDs act as peroxisome proliferator-activated receptors gamma (PPARγ) full agonists, which are also involved in the increase of adipocyte differentiation, fluid retention, weight gain, bone loss, and congestive heart failure." (PMID 27313601, 2016). "Thiazolidinedione, as PPARγ-specific agonists, can cause water retention, weight gain, peripheral edema, and congestive heart failure." (PMID 25360162, 2014). "Although it remains to be seen if the PPARγ agonism produces the same side effects that make currently available PPARγ agonists undesirable, such as weight gain, increased fluid retention, and a higher risk for the development of congestive heart failure." (PMID 38664391, 2024). "Currently, drug discovery programs targeting PPARγ have tried to design PPARγ partial modulators because PPARγ full agonists have serious adverse effects, such as fluid retention, congestive heart failure, bone fractures, and hepatotoxicity." (PMID 32054125, 2020). "Considering evidence showing desensitization to LPS is favorable in patients with chronic heart failure, our current data imply targeting PPARγ-mediated signaling with EETs would be a possible novel therapeutic approach to treat LPS-induced cardiac pathologies." (PMID 25426073, 2014). "PPARγ activators thiazolidinediones may trigger an aggravation of congestive heart failure, which counterbalances the cardiovascular potential benefit of these drugs." (PMID 19173749, 2009). "However, the use of PPARγ agonist in clinical practice is greatly limited as it could lead to water and sodium retention and hence result in congestive heart failure." (PMID 36518993, 2022).
Hypercholesterolemia (22 papers, 2012 to 2025). An increased concentration of cholesterol in the blood. "In summary, the experimental results indicate that the BYHWT alcohol precipitation, 50% alcohol, and 75% alcohol components can modulate the PPARγ/LXRα/ABCA1 pathway in hypercholesterolemia mouse model to promote CHO metabolism." (PMID 40678621, 2025). "Some increase in gene expression of CD36 and PPARg has occurred only in HUVECs incubated with lEVs isolated from hypercholesterolaemia patients." (PMID 39420340, 2024). "We also found altered DNA methylation in patients with hypercholesterolemia, in key genes associated with fatty acid transport and metabolism (hypomethylated: PPARD, PPARG, SLC27A1, SLC27A3 and SLC25A20, and hypermethylated: ANGPTL4, ACLS6, ACADM and CPT1A)." (PMID 33028190, 2020). "Therefore, this study was mainly conducted to confirm that different components of BYHWT reduced blood lipid levels in hypercholesterolemia mouse model through the PPARγ/LXRα/ABCA1 pathway." (PMID 40678621, 2025). "This study proved that the alcohol precipitation group and 75% group components can enhance RCT by upregulating the PPARγ/LXRα/ABCA1 signalling pathway, thus reducing the lipid level in hypercholesterolemia mouse model and improving lipid accumulation in hepatocytes." (PMID 40678621, 2025). "Therefore, the focus of this study was to investigate the mechanism of liver CHO accumulation induced by HFD in hypercholesterolemia mouse model and the effects of different components of BYHWT on the PPARγ/LXRα/ABCA1 pathway in these mice." (PMID 40678621, 2025). "We also aimed to further observe whether PPARγ agonists could reverse vascular endothelial dysfunction in hypercholesterolemia and, if possible, to determine whether or not this was related to the regulation of vascular MPO and subsequent restoration of NO bioavailability." (PMID 32190383, 2020). "However, whether PPARγ agonists can restore NO bioavailability by regulating MPO, thereby improving vascular endothelial function and delaying the progression of atherogenesis in hypercholesterolemia, have not been confirmed." (PMID 32190383, 2020).
multiple myeloma (22 papers, 2008 to 2025). "The Yang laboratory found that mature adipocytes in bone marrow protect myeloma cells against chemotherapy through autophagy activation and that myeloma-associated adipocytes contribute to bone disease through PPARγ, EZH2, and PRC2-related mechanisms." (PMID 33498240, 2021). "FBXO9 may be associated with patient survival in multiple myeloma, is linked to adipocyte development, and targets peroxisome proliferator-activated receptor gamma (PPARγ) for degradation." (PMID 34480022, 2021). "We have previously shown in chronic myeloid leukemia and multiple myeloma studies that CLF modulates PPARγ ubiquitin ligase activity, which results in ROS-mediated apoptosis." (PMID 41303378, 2025). "In multiple myeloma, the overexpression of PPARγ induced apoptosis through the inhibition of Interleukin-6 production." (PMID 35954274, 2022). "Meanwhile, inhibition of PPARγ using lentivirus transfection of shRNA in human myeloma cell lines showed that the facilitation of PPARγ blocked angiogenesis and PPARγ repressed vascular endothelial growth factor (VEGF) transcription." (PMID 35341213, 2022). "Next, we compared the anti-myeloma efficacy of CLF with that of other Peroxisome Proliferator Activated Receptor Gamma (PPARg) agonists - rosiglitazone and pioglitazone." (PMID 35646666, 2022). "PPARγ overexpression in myeloma cells decreased cell proliferation, induced spontaneous apoptosis even in the absence of exogenous ligand, and enhanced their sensitivity to PPARγ ligand-induced apoptosis." (PMID 20204067, 2010). "PPARγ and its ligands effectively blocked IL-6 transcription and secretion from BMSCs that is induced in response to myeloma cell adhesion." (PMID 20204067, 2010). "Overexpression of PPARγ in myeloma cells and BMSCs inhibited both basal and myeloma cell adhesion-induced IL-6 production by BMSCs." (PMID 20204067, 2010). "Taken together, the results of these studies demonstrate that PPARγ agonists can be used to inhibit IL-6-dependent crosstalk between myeloma cells and BMSCs, validating novel therapeutic strategies that target the tumor-stromal microenvironment." (PMID 20204067, 2010). "In conclusion, these findings validate PPARγ as a targetable conduit in triple-negative and ER-positive breast cancers and open new opportunities for co-targeting PPARγ and HDACs using repurposed anti-diabetic (rosiglitazone) and anti-myeloma/lymphoma (LBH589 and SAHA) drugs." (PMID 34580286, 2021). "In addition, our laboratory demonstratedthat human multiple myeloma cells modestly express PPARγ." (PMID 18528522, 2008). "Our findings are consistent with single cell qRT-PCR analysis of normal MSCs exposed to myeloma cells, which exhibit trends for suppression of LEPR and PPARG." (PMID 33680918, 2020). "We have previously reported that the PPARγ agonist pioglitazone (PIO) enhances, in-vitro, the cytotoxic effect of the Histone deacetylase inhibitor (HDACi), valproic acid (VPA), on multiple myeloma cells." (PMID 26091518, 2015). "Furthermore, PPARγ overexpression-induced cell death of myeloma cells is not abrogated by coculture with BMSCs." (PMID 20204067, 2010).
Myocardial fibrosis (22 papers, 2013 to 2026). "PPARγ expression is closely associated with myocardial fibrosis, due to its involvement in regulating inflammation, energy metabolism, and oxidative stress." (PMID 35799890, 2022). "In the present study, we provide the first evidence for cardiac protective roles of irbesartan in the ACE2 deficiency-mediated pathological hypertrophy, myocardial fibrosis and cardiac injury via activation of the PPARγ signaling pathway." (PMID 24067190, 2013). "In this work, we directly assessed the hypothesis that irbesartan would exert its protective effects on ACE2 deficiency-mediated myocardial fibrosis and cardiac injury by the modulation of the PPARγ signaling pathway." (PMID 24067190, 2013). "We conclude that irbesartan prevents ACE2 deficiency-mediated pathological hypertrophy and myocardial fibrosis in ACE2 mutant mice via activation of the PPARγ signaling and suppression of the TGFβ−CTGF−ERK signaling, resulting in attenuation of myocardial injury." (PMID 24067190, 2013). "We hypothesized that irbesartan would exert its protective effects on ACE2 deficiency-mediated myocardial fibrosis and cardiac injury via the PPARγ signaling." (PMID 24067190, 2013). "Key signaling pathways associated with myocardial fibrosis include the TGF-β/Smad, mitogen-activated protein kinase (MAPK), and peroxisome proliferator-activated receptor gamma (PPAR-γ) pathways." (PMID 40242436, 2025). "Recent studies have shed light on the regulatory role of PPARγ activation in modulating miRNAs involved in inflammation and myocardial fibrosis." (PMID 41149642, 2025). "PPARγ activation alleviates oxidative stress and myocardial fibrosis by inhibiting the NF-κB axis and transforming growth factor-beta 1/suppressor of mothers against decapentaplegic (TGF-β1/Smad) pathways, thereby improving cardiac function." (PMID 40734976, 2025). "In conclusion, our data revealed that the CXCR4 orchestrates a pro-inflammatory phenotype in macrophages by repressing PPARγ activity, thereby aggravating inflammatory response, myocardial fibrosis, and cardiac dysfunction." (PMID 35173552, 2022). "Stimulation of PPARγ inhibits cellular inflammatory response, suppresses myocardial fibrosis, and improves cardiac diastolic dysfunction in diabetic hearts." (PMID 34336956, 2021). "In a HF rat model, the PPARG agonist, pioglitazone, has also been shown to prevent myocardial fibrosis and HF development through the suppression of the Wnt-β-catenin signaling pathway." (PMID 31850068, 2019). "At the same time, accumulating evidences demonstrate that PPARγ exerts a broad spectrum of biological functions, including the beneficial effects of alleviating myocardial fibrosis." (PMID 27293418, 2016). "Statins such as atorvastatin exert cardioprotective effects by inhibiting the advanced glycation end-products-receptor for advanced glycation end-products-extracellular signal-regulated kinase 1/2 signaling pathway through PPARγ, thereby reducing myocardial fibrosis." (PMID 40734976, 2025). "Furthermore, it has been reported that targeting miR-199b, a fibrosis-promoting miRNA elevated when PPARγ is suppressed, alleviated myocardial fibrosis in experimental models." (PMID 41149642, 2025). "Previous research has confirmed that PPARγ possesses anti-myocardial fibrosis functionality." (PMID 38643140, 2024). "Moreover, activating PPARγ improved myocardial cell injury by reducing myocardial fibrosis and cardiomyocyte apoptosis induced by ischemia/reperfusion." (PMID 37033616, 2023). "Previous studies demonstrated that PPARγ agonists could improve diastolic function and reduce myocardial fibrosis in diabetic hearts." (PMID 34336956, 2021). "Finally, activation of PPARγ inhibits isoprenaline- induced myocardial fibrosis and remodeling via the NF-κB and MAPKs-dependent mechanism in rats." (PMID 27293418, 2016). "The characteristics of PPARγ regulate myocardial fibrosis in different CVDs." (PMID 27293418, 2016).
Myocardial fibrosis (continued). "These suggest that the underlying mechanism may be varied from different drugs, but PPARγ play a critical role in myocardial fibrosis after MI is indisputable." (PMID 27293418, 2016). "Therefore, more research needs to prove the role of different PPARγ subtypes in myocardial fibrosis." (PMID 27293418, 2016). "Besides, study on experimental animals demonstrated that tenascin-x, an ECM glycoprotein exclusively expressed in fibroblasts, can inhibit myocardial fibrosis via upregulation of TGFβ1 and downregulation of PPARγ in alcoholic cardiomyopathy." (PMID 27293418, 2016). "From molecular analyses, we concluded that the reverse process of myocardial fibrosis was dependent on upregulation of PPARα and PPARγ expression, downregulation of NF-κB expression, and suppressing TNF-α, ICAM-1, and MCP-1 production through the NF-κB signaling pathway." (PMID 24171042, 2013). "In diabetic cardiomyopathy models, PPARγ agonists such as pioglitazone and rosiglitazone have been shown to downregulate TGF-β/ERK signaling and inflammatory cytokines, resulting in reduced myocardial fibrosis, possibly via miRNA-mediated control of epithelial-to-mesenchymal transition pathways." (PMID 41149642, 2025). "Thus, on one hand, whether the activation of PPARγ which could attenuate myocardial fibrosis remains unclear, the improving of cardiac function may not be related to the attenuation of cardiac fibrosis." (PMID 27293418, 2016).